EGFR (epidermal growth factor receptor)
Diseases named in the same sentence as EGFR in open-access papers (continued):
Sharing a sentence is not in itself a finding about the gene and the disease.
adenocarcinoma (continued). "The older group (≥80 years) of patients with NSCLC included significantly higher rates of non-adenocarcinoma, wild-type EGFR, KRAS mutations, and smokers." (PMID 25152277, 2014). "Activation of the EGFR pathway mediated by activating mutations in its constituents is a key driver in adenocarcinomas of the lung, mediating important carcinogenic properties such as cell-cycle progression, apoptosis, angiogenesis and metastasis." (PMID 24593867, 2014). "EGFR mutation testing was feasible in 100% of evaluable patients and its incidence was 40.8%, 7.9% and 14.3% in adenocarcinomas, squamouscarcinomas and NSCLC NOS subgroup respectively." (PMID 24205040, 2013). "EGFR mutations were detected in 179 (13.5%) patients, with female and adenocarcinoma histology predominance." (PMID 23934203, 2013). "Given that the overwhelming majority of patients in our study had adenocarcinoma (96%) and all patients were from India, it is impossible to comment on the correlation of pathology or ethnicity to EGFR mutation status." (PMID 23620765, 2013). "We found a higher rate of EGFR mutation in adenocarcinomas than over all (29.8% vs 20%) and among women than men (32% vs 23%), similar to Korean, Chinese and Japanese data." (PMID 24124538, 2013). "The adenocarcinoma subtype and hMLH1 overexpression were two independent factors that relate to EGFR mutations (p<0.0005 and p=0.013), but gender and smoking history do not (p=0.070 and p=0.538)." (PMID 24205245, 2013). "XL647 demonstrated antitumor activity in patients with EGFR-activating mutations and adenocarcinoma histology (41 patients) in a phase II study with most common adverse effects being diarrhea, nausea, and fatigue." (PMID 23936861, 2013). "In our French population, the EGFR mutation prevalence is higher in older patients, women, adenocarcinomas and TTF-1 expressing adenocarcinomas." (PMID 23934203, 2013). "Among the patients with adenocarcinoma, 220 cases were found to harbour at least 1 mutation in the EGFR gene." (PMID 23590575, 2013). "For example, constitutively active mutations of epidermal growth factor receptor (EGFR) gene are often associated with well differentiated adenocarcinoma of the lung showing bronchioloalveolar pattern." (PMID 23617234, 2013). "The positivity of EGFR mutation in adenocarcinoma, as confirmed by microdissection analysis, was 91.8%." (PMID 23418425, 2013). "Several studies have reported KRAS mutant signatures or differentially expressed genes between adenocarcinomas with EGFR and/or KRAS mutations and respective wild type cases." (PMID 24205279, 2013). "If we assume that 50% of Asian adenocarcinoma patients carry EGFR mutations, the expected detection rate in an Asian study population comprising 80% adenocarcinoma patients should be 40%." (PMID 23927790, 2013). "A previous study showed an acquired PIK3CA mutation in SCLC transformed from EGFR-mutated adenocarcinoma after EGFR-TKI therapy." (PMID 24195468, 2013). "This study of 907 patients (largest single cohort study from India) showed an overall 23% EGFR mutation, with a rate of 26% in adenocarcinoma, in Indian population that closely approximates the rate in Japanese and East Asian countries." (PMID 24124538, 2013). "EGFR mutated tumors are typically adenocarcinomas, where mutations can be identified in approximately a quarter of cases, and in a higher proportion of tumors from Asian patients." (PMID 24376723, 2013). "Together, this suggests that the overall genomic and transcriptional landscape of adenocarcinoma is affected, but only to a minor extent, by the mutational status of EGFR and KRAS." (PMID 24205279, 2013). "In concordance with previous reports, the EGFR mutation rate in adenocarcinoma patients (44.2%, 42/95) was much higher than that in non-adenocarcinoma patients (8.0%, 9/113; P = 0.000)." (PMID 23341890, 2013). "In 101 evaluable samples, we detected 25 samples with EGFR mutation, 20 out of 25 were adenocarcinoma." (PMID 24205040, 2013).
adenocarcinoma (continued). "Since then, given that many patients cannot receive second-line therapy after first-line failure because of their generally deteriorating condition, EGFR mutation testing is requested more frequently at the time of diagnosis for patients with adenocarcinoma." (PMID 23927790, 2013). "Mutations in the EGFR gene were found in 221 of 484 patients (45.7%) and were more frequent in women (60.6%, p<0.001) and in patients with adenocarcinoma histology (47.1%, p=0.004)." (PMID 23590575, 2013). "In the present study, we found that 10% of the 77 analyzed adenocarcinoma samples harbored EGFR mutations, 35% of which carried KRAS mutations, while 51% of the 54 samples analyzed for KRAS mutations were negative regarding both mutation types." (PMID 23817662, 2013). "Immunohistochemistry using mutation-specific mAbs is demonstrated to be a reliable test for detecting EGFR mutations in adenocarcinoma of the lung in our study." (PMID 23419122, 2013). "After adjustment, however, only adenocarcinoma histology was significantly associated with positive EGFR mutation (adjusted prevalence ratio = 2.91; 95% CI 1.34–6.32; P = 0.007)." (PMID 23468851, 2013). "In our series, the EGFR mutation prevalence was clearly higher for women with a TTF-1 positive adenocarcinoma (28.3%; 101/357)." (PMID 23934203, 2013). "Taken together, these results suggest a higher genomic complexity in EGFR-mutated adenocarcinomas compared with KRAS-mutated and EGFRwt/KRASwt tumors." (PMID 24205279, 2013). "EGFR mutations in SCLC mostly manifest as a “transformation” after EGFR-TKI therapy in EGFR-mutated adenocarcinoma, whereas primary SCLC with EGFR mutation is extremely rare." (PMID 24195468, 2013). "The low frequency of patients with adenocarcinoma in our study likely accounts for the low percentage of EGFR mutations detected in our group." (PMID 23892415, 2013). "Overexpression of hMLH1 and the adenocarcinoma subtype were both independent factors that related to EGFR mutations in NSCLCs (p=0.013 and p<0.0005)." (PMID 24205245, 2013). "TBLB of the primary tumor was performed again, and only adenocarcinoma with the EGFR L861Q mutation was detected." (PMID 24195468, 2013). "Differentially expressed genes between EGFR/KRAS mutation groups in ≥4 of five Affymetrix adenocarcinoma cohorts." (PMID 24205279, 2013). "Women, former smokers, those with better mobility when admitted for diagnostic work-up, and those with stage IV disease or adenocarcinoma histology were significantly more likely to have EGFR mutation testing requested." (PMID 23468851, 2013). "KRAS positive mutations are limited to NSCLC (predominantly adenocarcinomas) and are mutually exclusive to mutations in EGFR and ALK." (PMID 23109866, 2012). "The frequency of EGFR mutations has been studied most extensively in East Asian populations, where it varies from 36.4 to 66.3 % in adenocarcinoma (ADC)." (PMID 22528563, 2012). "The frequency of EGFR mutation in adenocarcinoma showed wide variation among different reports (3%-59.7%); this was related to ethnicity, gender, and smoking status." (PMID 22695392, 2012). "Adenocarcinoma of esophagogastric junction rarely presents EGFR mutation, especially gefitinib-associated mutations such as L858R, or delE746-A750." (PMID 22252115, 2012). "Eleven NSCLC patients with adenocarcinomas harbored activating EGFR mutations, including E746-A750del and L858R, and became refractory to treatment with gefitinib." (PMID 22815900, 2012). "A study from Japan evaluated 447 resected adenocarcinoma specimens for ER expression and its association with EGFR mutations." (PMID 24213497, 2012). "Patient characteristics included a median age of 66 years (range, 48–78 years), stage IV disease (nine cases), adenocarcinoma (seven cases) and activating mutation-positives in the epidermal growth factor receptor gene (two cases)." (PMID 22809298, 2012).
adenocarcinoma (continued). "The fusion gene has been observed predominantly in adenocarcinomas (4–7%) and is mutually exclusive with mutations in the EGFR, K-ras, and ERBB2 genes." (PMID 22363766, 2012). "NSCLC large cell and adenocarcinoma patients should be tested at diagnosis for EGFR mutations as those who exhibit such mutations benefit from EGFR inhibitors (e.g. erlotinib or gefitinib) in the first-line setting, as recommended by NCCN guidelines." (PMID 22363766, 2012). "A possible explanation is that in adenocarcinoma and in Asiatic patients there is a high incidence of EGFR mutations that are considered a positive prognostic factor." (PMID 27398239, 2012). "Adenocarcinoma with an EGFR gene mutation (exon 19 deletion L747-E749; A750P) was detected in a transbronchial biopsy specimen; the patient was diagnosed with stage IV (cT2N2M1b) non-small cell lung cancer (NSCLC)." (PMID 23079208, 2012). "Available data suggest that K-RAS mutations represent a negative prognostic factor particularly in patients populations with high incidence of EGFR mutations, such as in adenocarcinoma and in Asiatic patients." (PMID 27398239, 2012). "In contrast, the most recent NCCN guidelines (version 1.2012) recommend ALK rearrangement testing concurrent with EGFR mutation testing for adenocarcinomas, large cell carcinomas and NSCLC NOS." (PMID 22825000, 2012). "We report a 39-year-old patient diagnosed as adenocarcinoma harboring EGFR mutation and EML4-ALK fusion gene." (PMID 23181703, 2012). "In this case report we describe the case of a patient with multiple bone metastases of NSCLC, adenocarcinoma with exon 21 point-mutation of EGFR, treated with gefitinib." (PMID 29147277, 2012). "It is almost exclusive to adenocarcinoma histology and mutually exclusive in patients with epidermal growth factor receptor (EGFR) or KRAS mutations." (PMID 25031935, 2012). "The fusion gene has been observed predominantly in adenocarcinomas (∼1.5%) and is mutually exclusive with mutations in the EGFR, K-ras, and EML4-ALK genes." (PMID 22363766, 2012). "This view is supported by data from EGFR inhibitor studies as such, EGFR-mutated adenocarcinoma represent a unique clinical entity necessitating molecular diagnostics for therapy guidance." (PMID 22140428, 2011). "EGFR mutations were identified in 13 (10.5%) of fully evaluated cases (11 in adenocarcinoma and two in NSCLC-NOS) including two novel mutations." (PMID 21949883, 2011). "It is elucidated recently that about half of adenocarcinomas in eastern Asian patients carry EGFR (epidermal growth factor receptor) activating mutation, which renders better prognosis." (PMID 22185633, 2011). "EGFR mutation was detected in 10 EBUS-TBNA biopsy samples which were confirmed adenocarcinoma on cytological level." (PMID 21418631, 2011). "In western countries, KRAS mutation rate is high in NSCLC patients, especially in those with adenocarcinoma (30%-50%), but EGFR mutation rate is low (3%-8%)." (PMID 21414214, 2011). "Recently, the results of studies exclusively focusing on EGFR-mutated adenocarcinoma have also been reported." (PMID 21165163, 2010). "Mutations of KRAS also target adenocarcinoma histology, but otherwise differ from EGFR mutations because they are relatively rare in East Asians and occur more frequently in males and smokers." (PMID 19238210, 2009). "To do so, we compared genetic profiles between EGFR mutated adenocarcinomas (ADC) and KRAS mutated ADC from 24 women with localized lung cancer." (PMID 18549475, 2008). "We detected a L858R EGFR mutation in the initial biopsies obtained from a 74-year-old white woman affected by an advanced adenocarcinoma with bronchioalveolar and papillary features." (PMID 17973572, 2007). "Adenocarcinomas in East Asian patients demonstrated a higher occurrence of EGFR mutations than in other ethnicities." (PMID 16552419, 2006).
adenocarcinoma (continued). "In the present study, we identified EGFR mutations in 136 of 322 adenocarcinomas (42.2%) from Japanese patients, and confirmed these previous observations." (PMID 16552419, 2006). "Patients who were EGFR mutation-positive were mostly women (61%) and had adenocarcinomas (87%), and significantly lower smoking index (34%)." (PMID 17106442, 2006). "In this study, we established a simple screening method to identify a deletion of exon 19 and a point mutation of exon 21 of the EGFR gene, and we detected these mutations in 136 cases (42.2%) with adenocarcinoma and two cases with other cell types." (PMID 16552419, 2006). "Epidermal growth factor receptor mutations were exclusively observed in adenocarcinoma patients; the incidence of EGFR mutations in adenocarcinoma patients was 55.6% (60/108)." (PMID 16052218, 2005). "In conclusion, adenocarcinomas with EGFR mutation had a distinctive clinico-pathological feature unrelated to smoking." (PMID 16052218, 2005). "Adenocarcinomas with EGFR mutations negatively correlated with K-ras mutations that are known to be associated with smoking." (PMID 16052218, 2005). "Most had adenocarcinoma and EGFR exon 19 deletions or L858R mutations." (PMID 40029742, 2025). "These cases were considered TRU-type adenocarcinomas and frequently harbored EGFR mutations." (PMID 38710944, 2025). "Furthermore, the acinar subtype adenocarcinoma had a higher EGFR mutation rate than solid subtype adenocarcinoma (P=0.0007) and lepidic subtype adenocarcinoma (P<0.0001)." (PMID 40182027, 2025). "The higher incidence of adenocarcinoma in females may be related to estrogen-mediated cell proliferation, exposure to secondhand smoke (which is more likely to induce adenocarcinoma), and genetic mutations (e.g., higher EGFR mutation rates)." (PMID 41584579, 2025). "Adjuvant osimertinib in resected high risk EGFR mutation locoregional adenocarcinoma of lung." (PMID 40949479, 2025). "Likewise, despite statistical adjustments for the number of patients with adenocarcinoma, the possibility of a sex-based imbalance in actionable driver mutations (e.g. EGFR, ALK) within our cohort and its impact on key endpoints cannot be excluded." (PMID 41218384, 2025). "Around 35–70% of patients with NSCLC might exhibit elevated CEA levels at the time of diagnosis, particularly in cases involving adenocarcinoma subtypes and EGFR mutations." (PMID 40712559, 2025). "EGFR mutations can indeed occur in adenosquamous carcinomas and in a minority of pure squamous cell carcinoma patients, although their response to tyrosine kinase inhibitors (TKIs) is typically shorter compared to adenocarcinoma patients." (PMID 40517166, 2025). "We found EGFR gene mutations in 8.5% of patients, in line with frequencies reported in Spain and western countries, when taking into consideration that in our series 69.9% were men and only 68.2% adenocarcinomas." (PMID 40591555, 2025). "Prior research has demonstrated that adenocarcinoma is more prone to EGFR mutations." (PMID 41573643, 2025). "Late-stage adenocarcinoma patients with EGFR mutations may harbor other mutated protooncogenes or dysregulated tumor suppressor genes." (PMID 40076686, 2025). "However, it is also known that brain metastasis-associated edema is more aggressive in adenocarcinoma patients with mutations such as EGFR or ALK when compared to other NSCLC types." (PMID 40428276, 2025). "For example, EGFR mutations have been associated with a predilection for brain involvement in adenocarcinoma, while KRAS mutations may favor hepatic spread." (PMID 41294679, 2025). "Interestingly, we found that EGFR mutation occurred more frequently in adenocarcinoma with rhabdomyoid differentiation." (PMID 40182027, 2025). "Also, the papillary subtype adenocarcinoma had a higher EGFR mutation rate than solid (P=0.0358) and lepidic (P=0.0269) subtype adenocarcinoma." (PMID 40182027, 2025).
adenocarcinoma (continued). "Adenocarcinoma, which is often associated with environmental and genetic factors such as smoking and mutations in EGFR and ALK genes, may be more susceptible to the protective effects of Albumin, which helps maintain cellular integrity in the presence of OS." (PMID 40719999, 2025). "Hence, it is worth screening adenocarcinoma for EGFR mutations as it has significant implications for the management of the disease." (PMID 40104451, 2025). "EGFR exon 19 mutations were significantly more common in adenocarcinoma cases (p = 0.003)." (PMID 40870512, 2025). "In NSCLC adenocarcinomas, more than 85% of common EGFR mutations confer sensitivity to EGFR‐tyrosine kinase inhibitors (TKIs), while the remaining ∼15% represent rare or uncommon EGFR mutations." (PMID 41020040, 2025). "The model demonstrates robust performance across specimen types (biopsies and surgical resections, 0.804 and 0.912, respectively), histologic subtypes (adenocarcinoma and non-adenocarcinoma, 0.880 and 0.801, respectively), and EGFR mutation subtypes (AUROC, 0.854–0.931)." (PMID 41211715, 2025). "EBUS-TBNA confirmed metastatic EGFR exon 21-mutated adenocarcinoma coexisting with pleural TB." (PMID 41141063, 2025). "He had been diagnosed with lung EGFR-mutated adenocarcinoma 28 months earlier." (PMID 41373665, 2025). "Of the adenocarcinoma cases, 18 patients were identified with EGFR mutations." (PMID 40260627, 2025). "Notably, in Asian populations, over 50% of advanced adenocarcinomas harbor activating epidermal growth factor receptor (EGFR) mutations." (PMID 39851952, 2025). "The diagnosis of adenocarcinoma (epidermal growth factor receptor (EGFR) mutation exon 19 deletion, programmed death ligand 1 (PD-L1) <1%, c-ros oncogene (ROS1) negative, anaplastic lymphoma kinase (ALK) negative) was established through pleural fluid cytology and bronchoscopy." (PMID 39479150, 2024). "Case 2: The patient was diagnosed with adenocarcinoma with EGFR L858R mutation." (PMID 38996163, 2024). "Moreover, the frequency of EGFR 19-Del mutations (22.54%) and EGFR 21 L858R mutations (24.25%) in patients with adenocarcinoma was higher than in patients with other types of NSCLC (all P< 0.001)." (PMID 39364008, 2024). "However, in patients with adenocarcinomas, the EGFR mutated patients tend to have lower TLS density(p = 0.014) than EGFR wild-type." (PMID 38528507, 2024). "In patients with EGFR mutations, the most common histological type was adenocarcinoma (p = 0.04)." (PMID 39768319, 2024). "Most EGFR mutations (95.45%) were found adenocarcinomas (p = 0.007)." (PMID 38783331, 2024). "In addition, combined SCLC, especially combined with adenocarcinoma component would complicate such cases with EGFR mutations." (PMID 37436674, 2024). "The total prevalence of EGFR mutations was 11.3% (14.9% in adenocarcinoma)." (PMID 39083479, 2024). "Signature SBS40a, with unknown cause, was found in most samples and accounted for the largest proportion of single base substitutions in adenocarcinomas, being enriched in EGFR-mutated cases." (PMID 38798417, 2024). "Case 1: The patient was diagnosed with adenocarcinoma with EGFR L858R mutation." (PMID 38996163, 2024). "Furthermore, the mutation rate of EGFR in 771 adenocarcinoma patients (n = 407, 52.79%) was higher than that in patients with other types of NSCLC (P < 0.001)." (PMID 39364008, 2024). "Furthermore, subsequent BM was more common in patients with adenocarcinoma histology (p = 0.001), EGFR-activating mutations (p < 0.001), and bone metastases at diagnosis, especially with spine involvement (p < 0.001)." (PMID 38256412, 2024). "EGFR mutation contributes to approximately 50% of mutations in Asian subjects with adenocarcinoma." (PMID 39513892, 2024).